ANLN (anillin, actin binding protein)
Diseases named in the same sentence as ANLN in open-access papers (continued):
Sharing a sentence is not in itself a finding about the gene and the disease.
oral cancer (3 papers, 2021 to 2022). "In summary, ANLN was overexpressed and associated with patient prognosis in oral cancer." (PMID 34082790, 2021). "The identification of the clinical importanceof ANLN in a large cohort of oral cancer specimens will further support the data from TCGA database." (PMID 34082790, 2021). "In this study, we analyzed ANLNexpression data in TCGA database and found that ANLN was overexpressed in oral cancer specimens compared to adjacent normal control specimens." (PMID 34082790, 2021). "The present data demonstrated that signaling molecules, including PI3K, PDK1, Akt and mTOR, were regulated by ANLN in oral cancer." (PMID 34082790, 2021). "Our data were consistent with a previous study, and for the first time, we showedthe secretion of ANLN in oral cancer." (PMID 34082790, 2021). "In conclusion, reduced ANLN expression induced cell apoptosis in both CAL27 and HN30 cells, which suggests that ANLN inhibits cell apoptosis in oral cancer." (PMID 34082790, 2021). "In this study, to investigate the role of ANLN in oral cancer, we reduced the expression of ANLN in oral cancer cells and assessedproliferation, aggressiveness, apoptosis, and cell cycle progression in oral cancer cells." (PMID 34082790, 2021). "This suggests that knockdown or knockout of ANLN might be a good way to induce cell apoptosis in oral cancer." (PMID 34082790, 2021). "In this study, our data indicate that ANLN could also affect the activation of PI3K/mTOR signaling in oral cancer." (PMID 34082790, 2021). "Therefore, ANLN contributes to the activation of PI3K/mTOR signaling in oral cancer." (PMID 34082790, 2021). "Therefore, ANLN contributes to cell growth and proliferation in oral cancer." (PMID 34082790, 2021). "In both cell lines, ANLN knockdown blocked cell cycle progressionfrom the G1 phase to the S phase, but the effect was not significant, which suggests that ANLN has little influence on cell cycle progression in oral cancer." (PMID 34082790, 2021). "In this study, knockdown of ANLN did not significantly block the transition from theG1 phase to the S phase in oral cancer." (PMID 34082790, 2021). "ANLN was reported to promote the progression ofmany cancers, but its function in oral cancer is not known." (PMID 34082790, 2021). "It is possible that ANLN might not be a checkpoint that controlsthe cell cycle in oral cancer." (PMID 34082790, 2021).
prostate adenocarcinoma (3 papers, 2022 to 2024). "ANLN facilitates tumor immune evasion through different mechanisms, which involve T-cell exclusion in different cancer types and tumor-infiltrating immune cells in colon adenocarcinoma, kidney renal clear cell carcinoma, liver hepatocellular carcinoma, and prostate adenocarcinoma." (PMID 35991576, 2022).
acute myeloid leukemia (2 papers, 2025). Acute myeloid leukemia (AML) is a group of neoplasms arising from precursor cells committed to the myeloid cell-line differentiation. "Unlike solid tumors, the oncogenic role of ANLN in acute myeloid leukemia(AML) arises from distinct genetic alterations." (PMID 41573677, 2025).
cholangiocarcinoma (2 papers, 2024 to 2026). A carcinoma that arises from the intrahepatic biliary tree (intrahepatic cholangiocarcinoma) or from the junction, or adjacent to the junction, of the right and left hepatic ducts (hilar cholangiocarcinoma). "The box plots showed the significant upregulation of ANLN in the tumor tissues of six cholangiocarcinoma datasets." (PMID 41513610, 2026).
clear cell carcinoma of the kidney (2 papers, 2024 to 2025). "In clear cell renal cell carcinoma(ccRCC), ANLN modulates the PI3K/AKT/mTOR axis to reinforce malignant cellular behavior." (PMID 41573677, 2025). "In lung, breast, cervical, and clear cell renal cell carcinomas, inhibition of ANLN leads to increased expression of epithelial markers such as E-cadherin and decreased expression of mesenchymal markers including N-cadherin and vimentin, resulting in significantly reduced migration and invasio." (PMID 41573677, 2025). "ANLN is upregulated in both clear cell renal cell carcinoma(ccRCC) and urothelial carcinoma." (PMID 41573677, 2025).
diffuse large B-cell lymphoma (2 papers, 2022). "The results suggested that ANLN expression in cancer tissues exceeded that in corresponding normal tissues for lymphoid neoplasm diffuse large B-cell lymphoma, brain lower grade glioma (LGG), thymoma (THYM), skin cutaneous melanoma (SKCM), and testicular germ cell tumors (TGCTs)." (PMID 35568883, 2022).
gallbladder cancer (2 papers, 2024 to 2026). "ANLN has been reported to function as an upstream regulator of PI3K/AKT signaling to facilitate disease progression in gallbladder cancer." (PMID 41513610, 2026).
gastric tumors (2 papers, 2019 to 2022). "Indeed, in a previous study, ANLN was shown to be overexpressed in proliferative gastric tumors compared with aggressive and metabolic gastric tumors." (PMID 35568883, 2022).
head and neck carcinoma (2 papers, 2022 to 2025). A carcinoma that arises from the head and neck region. "ANLN contributes to the initiation and progression of head and neck cancers by modulating vascular activity and promoting tumor-associated macrophage polarization." (PMID 41573677, 2025).
kidney cancer (2 papers, 2022). Primary or metastatic malignant neoplasm involving the kidney. "Contrastingly, in patients with kidney cancer and melanoma, low ANLN expression was associated with clinical benefits derived from ICB therapy (PD-L1 or PD-1), and thus longer OS." (PMID 35991576, 2022). "Nevertheless, current research merely focuses on fixed types of cancer, and the potential effect of ANLN on commonly diagnosed gynecological tumors, like endometrial cancer, and malignant kidney tumors, which are characterized by multiple histological subtypes, is still unclear." (PMID 36199577, 2022).
mesothelioma (2 papers, 2022). A usually malignant and aggressive neoplasm of the mesothelium which is often associated with exposure to asbestos. "In pan-cancer prognostic analysis, Kaplan-Meier survival curves revealed a significant association of upregulated ANLN expression with poor OS in ACC, BLCA, BRCA, KIRC, KIRP, LIHC, LUAD, mesothelioma (MESO), and PAAD; contrastingly, low ANLN expression was associated with poor OS in THYM." (PMID 35991576, 2022).
oral squamous cell carcinoma (2 papers, 2022 to 2025). "IIn oral squamous cell carcinoma, ANLN knockdown increases expression of epithelial markers such as cadherin-1(CDH1) and claudin-1(CLDN1), while reducing mesenchymal markers including vimentin, SNAIL1, and SNAIL2, leading to attenuated EMT." (PMID 41573677, 2025).
renal aplasia (2 papers, 2017 to 2019). "Some cases of hydrocephalus and renal aplasia in ANLN‐mutant, ARDS‐affected Dalmatians were caused by abnormal assembly of intercellular junctions in the epithelium during early organogenesis." (PMID 30548429, 2019). "Unilateral renal aplasia may result from a developmental expression of ANLN." (PMID 28222102, 2017).
Sepsis (2 papers, 2022 to 2024). Sepsis is defined as life-threatening organ dysfunction caused by a dysregulated host response to infection. "We established a prognostic model consisting of four sepsis-related genes: KRT20, PAEP, CCR3, and ANLN." (PMID 39421149, 2024).
skin cutaneous melanoma (2 papers, 2022). "Among 181 mutants, R153Q/L mutation was detected in five cases (uterine serous carcinoma, LUAD, cutaneous melanoma, mucinous adenocarcinoma of the colon and rectum, and HNSC) and induced a frame-shift mutation in ANLN, resulting in truncation of the protein." (PMID 35568883, 2022). "We found that the frequency of ANLN alterations was the most common in UCEC (mutated in 7.18% of cases), followed by skin cutaneous melanoma (4.95%)." (PMID 35568883, 2022).
urothelial carcinoma (2 papers, 2019 to 2025). A malignant neoplasm derived from the transitional epithelium of the urinary tract (urinary bladder, ureter, urethra, or renal pelvis). "ANLN showed overexpression in basal-like urothelial carcinoma cell lines and patients, while TLE2 showed significantly higher expression in luminal-like urothelial carcinoma cell lines and patients." (PMID 31766561, 2019). "Furthermore, higher ANLN expression correlates with worse patient prognosis in both ccRCC and urothelial carcinoma." (PMID 41573677, 2025).
adenoma (1 paper, 2022). A neoplasm arising from the epithelium. "We showed that genes ANLN, CDK1, ECT2, and TNC were associated with adenoma progression to carcinoma, ANLN and PDGFD with development of metastases, while genes ANLN, CDK1, ECT2, and PDGFD were associated with the level of malignancy." (PMID 36362041, 2022). "We identified statistically significant differences between the adenoma and adenoma with early carcinoma for ANLN (p ≤ 0.001), CDK1 (p ≤ 0.05), ECT2 (p ≤ 0.01), and TNC (p ≤ 0.05)." (PMID 36362041, 2022). "ANLN, CDK1, ECT2, and TNC were differentially expressed between adenoma and adenoma with early carcinoma." (PMID 36362041, 2022). "The genes TNC, CDK1, ANLN, and ECT2 were significantly upregulated in adenoma with early carcinoma when compared to adenoma and can be considered as potential biomarkers for malignant transformation." (PMID 36362041, 2022). "In adenomas with early carcinomas, statistically significant results include TNXB with 7.7-fold downregulation (p ≤ 0.001), 4.4-fold upregulation of CDK1 (p ≤ 0.01), 14.1-fold upregulation of ANLN (p ≤ 0.001), and 26.3-fold upregulation of ECT2 (p ≤ 0.001)." (PMID 36362041, 2022).
asthma (1 paper, 2021). "ANLN was upregulated in asthmatic who got cold compared to healthy who got colds, indicating its specificity to asthma exacerbation to viral infections." (PMID 34088958, 2021).
BO syndrome (1 paper, 2019). "This is the first study that has reported ANLN as a likely candidate pathogenic gene for BO syndrome in a three‐generation Chinese family." (PMID 30548429, 2019). "In this study, we identified, for the first time, a heterozygous missense variant in ANLN (NM_018685.4: c.G1105A; NP_061155.2: p.G369R) that is likely to be a candidate causative gene of BO syndrome in a specific Chinese family." (PMID 30548429, 2019). "Here, we describe the identification of a heterozygous missense variant (NM_018685.4: c.G1105A; NP_061155.2: p.G369R) in ANLN located in exon 6 in a three‐generation Chinese family with BO syndrome using whole‐exome sequencing, PCR‐Sanger sequencing and in silico analysis." (PMID 30548429, 2019). "Thus, our data suggested that the heterozygous variant c.G1105A in ANLN was a likely candidate disease‐causing variant in the Chinese family (JX‐001) with BO syndrome." (PMID 30548429, 2019). "However, the underlying role of ANLN in BO syndrome has not yet been illuminated." (PMID 30548429, 2019).
bone metastasis (1 paper, 2023). Transfer of a neoplasm from its primary site to bones. "Future studies would benefit from expanding sample sizes in a multicenter environment to establish a clearer relationship between the expression of METTL3, YTHDF1, ANLN and bone metastasis." (PMID 36923927, 2023).
brain tumors (1 paper, 2022). "As previous research has demonstrated, ANLN is ubiquitously overexpressed in diverse tumor tissues, except for brain tumors." (PMID 36199577, 2022).
breast invasive carcinoma (1 paper, 2021). "In addition, GEPIA analysis suggested that the expression level of ANLN was upregulated in 1,085 breast invasive carcinoma (BRCA) tissues when compared with 291 normal tissues." (PMID 34295807, 2021).
diabetes (1 paper, 2023). "The role of hsa-miR-503 in pathomechanism of diabetes complications depends on mitochondrial activity (DHFR), cell cycle control (CCNE2), cell protection (SOD2), podocyte migration (ANLN), inflammatory process (IL10, EFE2, VEGFA) and fibrosis (COL1A1), showing its contribution to CKD development." (PMID 36859746, 2023).
Fanconi anaemia (1 paper, 2022). "The pathway map showed that the cell cycle, nucleocytoplasmic transport, and Fanconi anaemia pathway were positively related to ANLN expression." (PMID 35340220, 2022).
lentivirus infection (1 paper, 2018). Virus diseases caused by the Lentivirus genus. "ANLN expression was determined by western blotting and qRT-PCR analysis in these two cell lines after lentivirus infection, and the results suggested that ANLN knockdown HCC cell models were successfully established." (PMID 30103211, 2018).
metastatic disease (1 paper, 2022). "ANLN expression increases as the tissues transition from normal to benign to malignant and, eventually, to metastatic disease." (PMID 36199577, 2022).
nephrotic syndrome (1 paper, 2025). A collection of symptoms that include severe edema, proteinuria, and hypoalbuminemia; it is indicative of renal dysfunction. "Even though ANLN has been linked to the nephrotic syndrome, the variant in the ANLN gene (c.886_887insTTC:p.Ser295_Pro296insLeu) was not reported previously." (PMID 40718208, 2025).
pulmonary disease (1 paper, 2017). "Our study reveals a novel pulmonary disease association for ANLN, provides new insights to pathophysiology and has enabled the development of a genetic test for breeding purposes." (PMID 28222102, 2017).
rectal cancer (1 paper, 2022). A primary or metastatic malignant neoplasm that affects the rectum. "In conclusion, a hypoxia score based on 5 hypoxia-related genes can be used to predict the prognosis of rectal cancer and ANLN with a cancer-suppressing effect and SRPX (Sushi Repeat Containing Protein X-Linked) with a cancer-promoting effect may be potential therapeutic targets for rectal cancer." (PMID 35548187, 2022). "ANLN may act as a tumor suppressor in hypoxia-mediated progression of rectal cancer." (PMID 35548187, 2022). "Our study found that ANLN was almost not expressed in neutrophils and low expressed in cancer tissues, which was related to the good prognosis of rectal cancer." (PMID 35548187, 2022).
sarcoma (1 paper, 2022). A usually aggressive malignant neoplasm of the soft tissue or bone. "In contrast, patients with LUSC or sarcoma (SARC) showed higher ANLN promoter methylation levels." (PMID 36199577, 2022).
Vertigo (1 paper, 2019). An abnormal sensation of spinning while the body is actually stationary. "Comparably, among the top genetic signals for symptom group 4, a group where are large proportion of the patients are characterized by hypotension (I95) and vertigo (R42), are ANLN that has been associated with systolic blood pressure." (PMID 31818369, 2019).
cancer (92 papers, 2009 to 2026). A tumor composed of atypical neoplastic, often pleomorphic cells that invade other tissues. "Extensive research has consistently indicated the upregulation of ANLN in diverse cancer types, along with its substantial associations with patient prognosis and cancer characteristics." (PMID 41427028, 2025). "Aberrant expression of ANLN has been closely associated with tumorigenesis and treatment resistance, making it an emerging focus in cancer drug resistance research." (PMID 41573677, 2025). "High ANLN expression is typically associated with tumor invasiveness and poor prognosis in various cancers." (PMID 40666516, 2025). "Dysregulations of ANLN is observed in a wide range of malignant tumors and its overexpression is closely linked to unfavorable outcomes in colorectal cancer, breast cancer, and liver cancer." (PMID 36030492, 2023). "Cytotoxic T lymphocyte‐associated antigen 4 (CTLA‐4), programed death 1 (PD‐1), and PD‐L1 were positively associated with ANLN expression in multiple cancers, including BRCA, KICH, KIRC, LIHC, PRAD, and THCA." (PMID 36030492, 2023). "Evidence has shown that ANLN promotes cell proliferation, and the loss of ANLN prevents the cancer cells from dividing and reduces their migration and invasion." (PMID 37007961, 2023). "In conclusion, our study found that ANLN was upregulated in diverse cancers and its aberrant expression was associated with pan‐cancer prognosis, MSI, TMB, the tumor immune microenvironment, and immune checkpoint genes." (PMID 36030492, 2023). "ANLN upregulation was detected in 21 types of cancers and was associated with poor overall survival (OS), disease‐free interval (DFI), and progression‐free interval (PFI) in most cancers except in THYM (Thymoma)." (PMID 36030492, 2023). "Numerous studies have suggested that ANLN is upregulated in many cancer types, as well as significantly associated with patient prognosis and malignant cancer characteristics." (PMID 35340220, 2022). "We found that ANLN expression was associated with cancer-associated fibroblasts in most tumor types." (PMID 35568883, 2022). "Recently, there has been sparse but accumulating evidence underpinning the association between ANLN expression and the development of different cancers." (PMID 36199577, 2022). "Abnormal ANLN expression causes dysregulation of cell division and is crucially involved in cancer development, cancer cell proliferation, and metastasis." (PMID 35991576, 2022). "Similar to the novel regulator function of ANLN in cell motility, recent studies also revealed the emerging role of ANLN in regulating cancer stemness, a phenotypic hallmark which shared many characteristics with cellular metastasis." (PMID 35340220, 2022). "We next analyzed the association of ANLN expression and cancer prognosis by utilizing one-way Cox regression analysis." (PMID 35340220, 2022). "In summary, our findings showed that ANLN is strongly associated with the prognosis, immune cell infiltration, gene mutations, and tumor treatment in patients with cancer." (PMID 35991576, 2022). "Previous studies had focused on the association between ANLN expression and the malignant progression of tumors, demonstrating that ANLN is upregulated in various cancers." (PMID 35340220, 2022). "In most cancer types, ANLN expression was found to be substantially linked with immune cell infiltration levels." (PMID 36199577, 2022). "Overall, these findings showed that ANLN expression was associated with prognosis in various types of tumors and that high ANLN expression was associated with poor prognosis in most cancers." (PMID 35568883, 2022). "After adjusting person neoplasm cancer status, ANLN and TTK levels in Cox model, AIM1L was identified as a risk factor for predicting OS in HCC patients (HR = 1.5, P = 0.037)." (PMID 34130591, 2021). "An association between ANLN expression and cancer susceptibility has been mainly inferred by gene expression studies." (PMID 33854062, 2021).